IL22 (interleukin 22)
Diseases named in the same sentence as IL22 in open-access papers (continued):
Sharing a sentence is not in itself a finding about the gene and the disease.
viral infections (continued). "Interleukins such as IL17A and IL22, which were upregulated at 3 dpi, are important to maintain mucosal immunity against virus infection and include induction of antiviral proteins, recruitment of neutrophils to infected areas and enhancement of mucosal barrier repair." (PMID 33110122, 2020). "The type III interferons (IFN-λs) are increasingly appreciated as the major interferon expressed in the context of viral infection of mucosal sites and have many structural and functional similarities with IL-22, another member of the IL-10 family of cytokines." (PMID 32637365, 2020). "There is substantial expression of IL-22 in the setting of viral infection, especially influenza." (PMID 32637365, 2020). "Accumulating evidence shows that IL-22 contributes to viral infection." (PMID 32843067, 2020). "Bacterial and viral infections resulted in increases in IL-22 expression in tissues." (PMID 33178219, 2020). "Collectively, these data suggest epithelial cells may optimize the beneficial effects of IL-22 through the induction of the IL-22 receptor during viral infection in the lung." (PMID 31416461, 2019). "Being that IL-22 is known to contribute to barrier maintenance and repair, this work may have implications for other viral infections in the lung that induce IFNβ." (PMID 31416461, 2019). "As such, these seemingly contradictory findings may indicate a double-edged role for IL-22 in viral infections, where this cytokine promotes pathogen spread to the CNS, but also limits inflammatory damage within the brain once the BBB has been breached." (PMID 30542269, 2018). "Genes typically associated with bacterial, but not viral infection, such as il8 (cxcl8a), tnfa, il22, were indeed not induced by SINV alone but were induced by Shigella, while mmp9 was also induced by SINV, as previously observed with CHIKV." (PMID 29881380, 2018). "It remains unclear whether IL-22 producing ILC3 and T cells are implicated in the tissue repair in our model, or whether they are implicated in the early phase of the viral infection in L. paracasei-fed mice." (PMID 28931041, 2017). "In addition, IL-22 deficit resulted in hypertrophy in the spleen and thymus, while over-expression of IL-22 in viral infections induced splenic and thymic atrophy, which most likely is a contributory mechanism for IL-22 to suppress T cell responses." (PMID 28634408, 2017). "To explore whether IL-22 plays a role in acute viral infection, we infected WT and IL-22−/− mice with the LCMV Armstrong (Arm) for 7 days." (PMID 28634408, 2017). "In addition to γδ T cells, hepatic DNT cells have also been proven to be another source of IL-22 during viral infection." (PMID 28634408, 2017). "The molecular mechanism of IL-22 production in γδ T cells during viral infection remains elusive." (PMID 28634408, 2017). "To date, whether IL-22 up-regulation in these distinct conditions is protective or pro-inflammatory is not clear; therefore, it is imperative to further define the mechanistic actions of IL-22 in viral infections." (PMID 28634408, 2017). "Viral infection triggered IL-22 production from liver, spleen and thymus tissues." (PMID 28634408, 2017). "To determine whether AhR regulates IL-22 production from γδ T cells in viral infection, we measured the effects of AhR inhibitor on IL-22 expression in hepatic γδ T cells at 3 dpi." (PMID 28634408, 2017). "Understanding the cytokine signature induced by a virus in a particular tissue in addition to defining signaling pathways induced by combinations of cytokines that include IL-22 will likely yield useful information required for predicting the impact of IL-22 in a particular viral infection." (PMID 27303405, 2016). "Should a more defined role for IL-22 during viral infections be elucidated, manipulating the production/availability of IL-22 could prove therapeutically beneficial in treatment and, possibly, prevention of viral-associated disease." (PMID 27303405, 2016).
viral infections (continued). "In contrast, IL-22 does not influence MCMV replication or neutrophil recruitment in the spleen, suggesting that the influence of IL-22 in a viral infection may depend upon the tissue microenvironment and/or IL-22-responsive cells." (PMID 27303405, 2016). "Although IL-17 and IL-22 mediate synergistic protective immunity in bacterial infection, the combination of these cytokines in viral infections may have pathological consequences." (PMID 27303405, 2016). "Thus, does IL-22 represent a useful therapeutic target for clinical intervention strategies for viral infections, and can we predict how IL-22 will influence an immune response induced by a particular virus?" (PMID 27303405, 2016). "However, it is clear that upon viral exposure, IL-22 is produced by a number of leukocytes in response to a broad array of virus infections." (PMID 27303405, 2016). "Overall, current data suggest that IL-22 may have an important role in a number of virus infections." (PMID 27303405, 2016). "Furthermore, IL-22 expression within the CNS has been demonstrated to increase following viral infection, and it is tempting to speculate that such increases result from local production of inflammatory cytokines." (PMID 30542269, 2018). "Together, our findings reveal a significant effect of the IL-23/PI3K/mTORC1 axis on regulating IL-22 production and also identify a novel role of IL-22 in controlling antiviral T cell responses in the non-lymphoid and lymphoid organs during acute and persistent viral infections." (PMID 28634408, 2017). "However, it remains unclear as to whether the signaling pathway regulates IL-22 production in viral infection." (PMID 28634408, 2017). "However, it is unclear whether the PI3K/mTORC1 signaling pathway is involved in modulating IL-23-induced IL-22 production in viral infection." (PMID 28634408, 2017). "Importantly, we found that IL-22 was crucial to restrict effector T cell responses, and contributed to the impediment of viral elimination in the liver and lymphoid organs during acute and persistent viral infections." (PMID 28634408, 2017). "In agreement with reports of IL-22’s damaging effects in lymphoid tissues observed in adenovirus delivery, our data show that excessive IL-22 prominently induces thymic and splenic atrophy in acute viral infection, leading to the inhibition of T cell development and detriment to immune functions." (PMID 28634408, 2017). "Finally, IL-22 restricts myocardial fibrosis induced by coxsackie virus infection, demonstrating the importance for IL-22 restriction of tissue damage and pathology that occurs as a consequence of viral infections." (PMID 27303405, 2016). "Thus, virus infection but not MT appears to be one of the causes of cell loss and IL-22 production by mucosal NKp44+ NK cells." (PMID 25759828, 2014). "Whether IL-22 plays a role in viral infection, however, is poorly understood." (PMID 22952908, 2012). "Singulex-Erenna®®, a standardized IL-22 peripheral blood assay, should be studied further not only for IBD and viral infections but also for neuropsychiatric pathology." (PMID 37628830, 2023). "However, our simultaneous observation of increased lung IL-22 concentrations may be ameliorating immunopathology, as previous research has demonstrated IL-22-mediated reduction of lung injury and promotion of airway repair in the context of sublethal viral infection." (PMID 37600776, 2023). "Like for other viral infections, HIV-1 and HBV, we demonstrated that in addition to innate immune responses, the cells of adaptative immune responses are involved in IL-22 production during SARS-CoV-2 infection." (PMID 35422799, 2022). "Collectively, our findings suggested that IL-22 dampens anti-ZIKV T cell responses in the periphery and exacerbates viral infection in the brain, leading to profound cerebral inflammation and animal paralysis and death." (PMID 32843067, 2020).
viral infections (continued). "However, the function and regulation of IL-22 in viral infection remain largely unknown." (PMID 28634408, 2017). "Conventional NK1.1+ NK cells and NK T cells secrete IL-22 in virus infections, and NK1.1 depletion during MCMV infection abrogated IL-22 protein production in the liver and lung." (PMID 24721575, 2014). "Moreover, IL-22 produced by ILC3 cells aids in repairing damage and protecting mice from intestinal viral infections." (PMID 39497434, 2024). "On the one hand, in most bacterial and viral infections involving epidermal remodeling and mucosal immunity, such as bacterial pneumonia, AIDS and influenza, Th22/IL-22 promotes host defense by mediating the innate immune response and maintaining epithelial barrier integrity." (PMID 36839448, 2023). "In this study, CASP8, IL22 and TLR3 were chosen to be used as target genes to assess the performance of the shortlisted reference genes, because these three genes play important roles in the innate immune response against virus infection." (PMID 32444639, 2020). "Further examination of lung T cells (CD3+CD5+ cells) showed no increase of IL-22 expression in L. paracasei-fed mice after 10 days of viral infection." (PMID 28931041, 2017). "Although IL-22 does not induce IFN-stimulated genes against viral infection within an in vitro cell culture system, it is capable of regulating antiviral T cell responses in the host." (PMID 28634408, 2017). "Collectively, experimental data point toward an important function of IL-22 production by NK cells during certain viral infections and suggest a role for cytokines, but not activation receptor ligation in inducing NK cell expression of IL-22." (PMID 27303405, 2016). "IL-22 neutralization does not impair protection from influenza infection in mice and, in certain viral infection models, can heighten inflammation without influencing virus clearance." (PMID 24721575, 2014). "More specifically, dysregulated IL-22–IL-22R pathway in the Anti-IL-22 Ab group contributed to cardiac viral replication, and decreased the level of IFN-γ, which was considered as the vital defenders against viral infection." (PMID 23050732, 2012). "Of course, some studies have shown that IL-22 may have a protective effect rather than a pro-inflammatory effect in certain viral infections." (PMID 40006939, 2025). "We also show that IL22 reduces the expression of viral entry receptors (e.g. ACE2, TMPRSS2, DPP4, CD46 and TNFRSF14), increases the expression of anti-viral proteins (e.g. RSAD2, AOS, ISG20 and Mx1) and, consequently, reduces the viral infection of neighboring cells." (PMID 34045640, 2021). "Importantly, IL-22-/- mice displayed significantly lower viral loads in both the spleen and brain at the peak of viral infection (13 dpi), but not at other time-points including 2, 7, and 20 dpi." (PMID 32843067, 2020). "Thus, our data suggest that LCMV infection elicits IL-22 expression from innate immune cells through the IL-23/PI3K/mTOR axis, and its production is essential for modulating antiviral T cell responses in both non-lymphoid and lymphoid tissues during acute and persistent viral infections." (PMID 28634408, 2017). "NK cells, which restrict MCMV replication in the spleen, liver, and lung, produce IL-22 in response to MCMV infection in the liver and lung but not spleen, demonstrating that IL-22 induction in systemic viral infection is organ-specific." (PMID 27303405, 2016).
Obesity (55 papers, 2011 to 2026). Accumulation of substantial excess body fat. "IL-22 also has been associated with elevated adipose inflammation in patients with obesity and after HFD15,20,21." (PMID 38383607, 2024). "Studies have shown that IL-22 deficiency led to increased bacterial translocation in mice, as well as worsening of metabolic parameters associated with obesity." (PMID 39203559, 2024). "Overweight/obesity was also linked to increased plasma levels of IL-5, IL-17A, IL-22, IL-33, TNF-α, and leptin and decreased levels of IL-10." (PMID 39902293, 2024). "Mice lacking the IL-22 receptor are more susceptible to HFD-induced obesity and IR, and treatment of obese mice with IL-22 suppresses TNF expression in adipose tissue, as well as improving IR." (PMID 39872860, 2023). "Although several cytokines have been associated with metainflammation in obesity and T2D, only a few show direct connection to the gut microbiota such as IL-22, IL-23, and IL-36." (PMID 33178196, 2020). "Our previous finding indicated that elevated serum IL-22 levels and Th22 frequencies were associated with insulin resistance in both obesity and T2D patients." (PMID 32849564, 2020). "Our previous findings indicated that elevated circulating levels of IL-22 and frequencies of Th22 cells were associated with insulin resistance in both patients with obesity and T2D." (PMID 32849564, 2020). "In obese mice IL-22 reduced ER/oxidative stress and improved the integrity of the mucosal barrier, and reversed microbial changes associated with obesity with an increase in Akkermansia muciniphila." (PMID 27350069, 2016). "IL-22 promotes intestinal health by regulating the function of intestinal epithelial cells and inhibiting lipid absorption, thus alleviating metabolic disorders associated with obesity to a certain extent." (PMID 41019044, 2025). "Moreover, IL-22 maintains intestinal integrity and barrier functions, and is linked to insulin resistance in obesity." (PMID 41273480, 2025). "Finally, our results elucidate how IL-22 or IL-22RA1 can be used to develop future tissue-specific treatments for obesity-associated metabolic disorders." (PMID 38383607, 2024). "In addition, serum levels of IL-22 have been associated to some extent with obesity, although research findings vary." (PMID 38734641, 2024). "Our study suggests that PTS administration could reverse the changes caused by an obesogenic diet in both IL-22 and AMPs, as one of the most plausible mechanisms explaining its protective effect against obesity." (PMID 35276798, 2022). "This study indicates that ILC3s and IL-22 in the pancreas may play a role in preventing obesity-associated type 2 diabetes." (PMID 35574038, 2022). "Evidence shows that IL-22 can directly modulate lipid metabolism by promoting lipolysis and enhancing fatty acid β-oxidation in adipose tissue and hepatocytes of obese mice, thus attenuating obesity-associated fatty liver and steatosis." (PMID 34944732, 2021). "Thus, Ss infection with obesity is characterized by lower systemic levels of IL-17, Type-1 associated cytokines and pro-inflammatory cytokines and higher systemic levels of IL-22 and Type-2 associated cytokines." (PMID 33042134, 2020). "To date, it remains unclear how IL-22 is regulated in humans, which physiological role circulating IL-22 levels exert and whether endogenous IL-22 levels are associated with protection against obesity and related disorders." (PMID 28143481, 2017). "Based on this evidence, our hypothesis is that IL-1, via IL-1R1, promotes the induction of intestinal ILC3 cells and reinforces the intestinal barrier through of the production of IL-22, as well as the improvement of metabolic and inflammatory changes associated with obesity and MS." (PMID 39203559, 2024). "Our results revealed that quercetin supplementation significantly mitigated obesity and chronic inflammation, and improved the disrupted gut barrier function through the actvation of AhR/interleukin 22 (IL-22) pathway." (PMID 40308638, 2025).
Obesity (continued). "We aim to compare the effects of REG3A and IL-22 expression by the epithelial cells on the development of obesity-related conditions and the composition of the microbiota." (PMID 41027972, 2025). "The levels of circulating IL-17 and IL-22 are found to be higher in individuals with obesity and T2DM." (PMID 41357227, 2025). "Obesity and high-calorie diets rapidly inhibit IL-22 production, leading to impaired gut barrier function, which exacerbates the risk of metabolic diseases." (PMID 41019044, 2025). "Administration of a long-acting IL-22-Fc fusion protein and recombinant IL-22 improved hyperglycemia in mouse models of obesity and reduced hepatic steatosis." (PMID 38811532, 2024). "IL-22 has been shown to restore insulin resistance in obesity by inhibiting pancreatic beta cell apoptosis and enhance insulin sensitivity by promoting peripheral white fat browning." (PMID 38734641, 2024). "IL-22 promotes heat production, renders mice resistant to reduction of body temperature induced by cold exposure, and reduces obesity induced by HFD." (PMID 38536726, 2024). "Interleukin (IL)-22 is critical in ameliorating obesity-induced metabolic disorders; however, it is unclear where IL-22 acts to mediate these outcomes." (PMID 38383607, 2024). "Research, on the other hand, lacks a clear explanation for the reduction of endogenous IL-22 serum or hepatic levels seen in male mice upon diet-induced MASLD or obesity challenge." (PMID 39156888, 2024). "IL-22 reduces liver damage during murine injury models but increases inflammation in adipose tissue from patients with obesity and type II diabetes." (PMID 38383607, 2024). "IL-22 is required for the prevention of obesity and IR through the regulation of triglyceride lipolysis and FAO in adipocytes." (PMID 39872860, 2023). "After high doses of IL-22-Fc administration (50–100 μg/mouse, twice weekly), the obesity was remarkably improved in DIO and db/db mice." (PMID 37525285, 2023). "Taken together, ambiguity and uncertainty enrich the efficacy and administration scheme of IL-22 in treating obesity, making it imperative to conduct additional studies concentrating on the mechanism and safety." (PMID 37525285, 2023). "Similar to the protective effect of ILC3s in obesity, ILC3-derived IL-22 protects against obesity-associated NAFLD through the improvement of hepatic lipid metabolism and inhibition of palmitate-induced primary hepatocyte apoptosis." (PMID 39872860, 2023). "An adipose tissue from patients with obesity and T2D produced specific enrichment of CD4+ T cells for IL-17 and IL-22, which is pathologically relevant to obesity-induced T2D." (PMID 36225181, 2022). "Overall, ILC3s are involved in the development of obesity and insulin resistance through the production of IL-22 and IL-17." (PMID 35574038, 2022). "Further, the expression of RORγt, lymphotoxin and IL-22 all elevated weight gain and adipose tissue size, paralleling findings that IL-22 from Th17 cells exacerbates inflammation in obesity." (PMID 35359972, 2022). "Lymphotoxin β receptor-deficient (Ltbr-/-) mice lack IL-23 and IL-22 and are resistant to diet-induced obesity, indicating that IL-23-IL-22 cytokine signaling regulates the microbiota, thus modulating weight gain and obesity." (PMID 34944732, 2021). "Production of rIL-22 by engineered Lactobacillus reuteri can also ameliorate hepatic steatosis in mice with diet-induced obesity, as evidenced by reduced triglyceride levels and liver weight via the IL-22/STAT3/Reg3 cascade." (PMID 34944732, 2021). "IL-22 can significantly reduce HFD-induced oxidative/ER stress and inflammation and reverse microbial changes associated with obesity." (PMID 34944732, 2021). "The largest impact of probiotic-mediated delivery of IL-22 in our model of diet-induced obesity was reduction of liver triglycerides." (PMID 32581074, 2020).